SP3 (Sp3 transcription factor)
Diseases named in the same sentence as SP3 in open-access papers (continued):
Sharing a sentence is not in itself a finding about the gene and the disease.
cancer (60 papers, 2007 to 2025). A tumor composed of atypical neoplastic, often pleomorphic cells that invade other tissues. "Actually, many previous studies have reported that apoptosis induced by various chemotherapeutic agents in a variety of cancer cells are often associated with “downregulation of Sp3” (detected by Western blot analysis) (51, –, 56)." (PMID 35019687, 2022). "We successfully introduced an approximately 100% DNA methylation ratio at the cancer‐associated gene SP3 in HEK293 cells." (PMID 36618443, 2021). "High levels of Sp1, Sp3, and Sp4 contribute to cancer cell development, survival, and migration to tissues, including the pancreas." (PMID 40758706, 2025). "Specificity proteins (Sp), members of the Sp/Kruppel-like factor family, demonstrate elevated expression patterns across various tumor and cancer cell lineages, with particularly pronounced expression observed for Sp1, Sp3, and Sp4." (PMID 41007866, 2025). "Peroxisome proliferator-activated receptor (PPAR): PPARƔ interacts with Sp1 (and Sp3) to regulate gene expression in both cancer and non-cancer cells, and most of these responses include interactions with other nuclear factors." (PMID 39858066, 2025). "Overexpression of the transcription factors Specificity protein 1 (Sp1) and Specificity protein 3 (Sp3) independently increases PDPN transcription in certain cancer cell lines." (PMID 39682237, 2024). "The pro-oncogenic functions of Sp1, Sp3 and Sp4 in cancer cell lines were studied in knockdown studies where silencing of each individual Sp TF decreased cancer growth, invasion and induced apoptosis." (PMID 36982239, 2023). "Recently, a genome-wide siRNA screen identified that the regulation of TNF-α mRNA expression by transcription factor SP3 is a critical factor for SMs mediated cancer cell death." (PMID 36831656, 2023). "This suggests that the process of cell transformation is accompanied by early induction of Sp1 and Sp3 prior to conversion of the muscle cell into a cancer cell." (PMID 36982239, 2023). "There is increasing evidence that Sp1, Sp3 and Sp4 play an important role in multiple cancers and their prognostic importance spans their functional pro-oncogenic activities alone and in combination with miRNAs and lncRNAs." (PMID 36982239, 2023). "The specificity protein (Sp) transcription factors (TFs) Sp1, Sp2, Sp3 and Sp4 exhibit structural and functional similarities in cancer cells and extensive studies of Sp1 show that it is a negative prognostic factor for patients with multiple tumor types." (PMID 36982239, 2023). "Despite these facts, anticancer agents that specifically target SpTFs are not being developed currently for clinical applications, even though several small molecules that are used for cancer and other chemotherapies also downregulate/degrade Sp1, Sp3 and Sp4." (PMID 36982239, 2023). "In this review, the role of Sp1, Sp3 and Sp4 in the development of cancer and their regulation of pro-oncogenic factors and pathways is reviewed." (PMID 36982239, 2023). "SP1 is critical for early embryonic development, but its expression decreases with age and there is evidence that the transformation of normal cells to cancer cells is associated with the upregulation of SP1, SP3, and SP4." (PMID 37998757, 2023). "A detailed study of the role of Sp1, Sp3 and Sp4 in cancer was investigated in multiple cancer cell lines by individual knockdown of the three genes and their combination coupled with analysis of the resulting functional and genomic effects and their overlap." (PMID 36982239, 2023).
cancer (continued). "Transfection of MCF-7 and MDA-MB-231 cancer cells with miRNA-20a, miRNA-106a and miRNA-106b antagomirs led to evident suppression in the levels of Sp1, Sp3, Sp4 and EZH2, but, simultaneously, there was an increase in the levels of ZBTB4." (PMID 36615262, 2022). "Similar to Sp1 and Sp4, Sp3 is often highly expressed in cancer cells, and knockdown of Sp3 in these cancer cells dramatically reduced cell proliferation and survival." (PMID 35019687, 2022). "SP3 is a transcription factor whose protein expression is usually higher in cancer cells than in normal cells." (PMID 34599150, 2021). "An antipsychotic drug, penfluridol, is currently used as an anti-cancer drug since it can downregulate the TFs like Sp1, Sp3, and Sp4." (PMID 32050495, 2020). "According to a few studies, BA inhibits the growth of cancer cells by stimulating proteasome-dependent downregulation of Sp1, Sp3, and Sp4." (PMID 32050495, 2020). "Some miRNAs over expressed in cancer, such as members of the miR-17-92 (miR-20a/miR-17-5p) and miR-27a clusters indirectly maintain high expression of Sp1, Sp3 and Sp4." (PMID 32050628, 2020). "Since EGFR expression is regulated by multiple factors, including specific protein (Sp) transcioption factors through interaction with HDAC1 and HDCA2 in cancer cells 19, 20, we tested the effect of Sp1 and Sp3 knockdown on EGFR activity and HDCA expressions." (PMID 32226300, 2020). "Increasing evidence has also shown that Sp1 and Sp3 are expressed at higher levels in a number of cancer cells than in normal cells, and knockdown of Sp1 or Sp3 in cancer cells dramatically reduced tumorigenic and metastatic phenotypes." (PMID 32641483, 2020). "A recent report showed that MALAT-1 is an Sp1-regulated gene and we therefore determined if ROS-inducing anticancer agents that downregulate Sp1, Sp3 and Sp4 in pancreatic and other cancer cell lines also decrease MALAT-1 expression." (PMID 29389953, 2018). "The functional and genomic effects of Sp1, Sp3 and Sp4 were investigated by RNAi in several different cancer cell lines." (PMID 26967243, 2016). "Studies in cancer cell lines show that Sp1, Sp3 and Sp4 are highly expressed, and RNA interference (RNAi) studies indicate that Sp transcription factors regulate genes associated with cell proliferation, survival and migration/invasion [reviewed in 14]." (PMID 26967243, 2016). "Sp1, Sp3 and Sp4 are overexpressed in many different cancer cell lines and high expression of Sp1 in tumors is a negative prognostic factor for breast, pancreatic, gastric, glioma, prostate and lung cancer patients' survival." (PMID 26317792, 2015). "Sp transcription factors play a role in the proliferation, survival, migration/invasion of several cancer cell lines and we used RNAi to investigate the differential effects of Sp1, Sp3, Sp4 and HULC knockdown on HCC cell proliferation and survival." (PMID 26317792, 2015). "Sp1, Sp3 and Sp4 are overexpressed in multiple cancer cell lines and tumor types and Sp-regulated genes and oncogenes play an important role in cancer cell proliferation, survival, angiogenesis and inflammation." (PMID 23194063, 2012). "Previous studies by RNA interference (RNAi) show that both survivin and bcl-2 are regulated by Sp1, Sp3 and Sp4 in cancer cells." (PMID 23110215, 2012). "Deregulated activity of transcription factors (TFs) of the Sp/KLF family, like Sp1, Sp3 and Sp4, and consequent over-expression of Sp-regulated genes occur frequently in human cancers." (PMID 22545098, 2012). "Both Sp1 and Sp3 show increased expression in a number of cancers suggesting that these transcription factors are switched back on during cancer cell differentiation." (PMID 19471608, 2008). "CENP-H can promote cancer growth and metastasis through PI3K/AKT, survivin, and mitochondrial apoptosis signaling mechanisms, and it can be regulated by long non-coding ribonucleic acid (lncRNA) plasmacytoma variant translocation 1 (PVT1)/miR-612, Sp1, or Sp3." (PMID 40071086, 2025).
cancer (continued). "The positive correlation of SP3 with various immune cell types and drug sensitivity indicates its potential role in modulating immune responses and therapeutic vulnerabilities, which has been observed in other cancers." (PMID 40128844, 2025). "Moreover, since Sp1, Sp3 and Sp4 regulate multiple genes required for cancer cell proliferation, survival and invasion, it has been suggested the Sp TFs are non-oncogene addiction genes." (PMID 39858066, 2025). "With few exceptions, lncRNA/miRNA pathways that lead to higher expression of Sp1, Sp3 and Sp4 result in downstream activation of pro-oncogenic genes/pathways, indicating that drugs targeting ncRNAs or Sp TFs should be highly effective anti-cancer agents." (PMID 36982239, 2023). "Transcription factors modulate the telomerase activity in cancer cells: The hTR gene promoter is activated by NF-Y, Sp1, pRB and HIF1; it is suppressed by Sp3 and signaling pathways such as JNK that cause a switch from Sp1 to Sp3 promoter binding." (PMID 37679807, 2023). "Genomic studies on these transcription factors and genes/pathways regulated by Sp1, Sp3 and Sp4 demonstrate their role in the growth, survival and migration/invasion of cancer cells and tumors, and this is consistent with their designation as non-oncogene addiction genes." (PMID 36982239, 2023). "We, therefore, hypothesized that HDAC inhibitors sensitize cancer cells to SMAC mimetics by enhancing TNF-α production via SP3." (PMID 36831656, 2023). "Normally, Sp1 and Sp3 are ubiquitously expressed in cells, and Sp4 expression is restricted to neuronal cells where it acts as a transcription activator; however, Sp4 expression has been found in many cancer cell lines such as the LNCaP." (PMID 35018219, 2022). "Levels of EGFR were found to be reduced in Sp1-knockdown or Sp3-knockdown cancer cells." (PMID 36615262, 2022). "SP3 is dysregulated in various cancers and is highly expressed in HCC." (PMID 34599150, 2021). "The influence of SP1 and SP3 expression on CGB expression in cancer is very difficult to assess." (PMID 31362717, 2019). "SP1 and SP3 expression level are often greater in cancer cells than in normal cells." (PMID 30386180, 2018). "We observed that the promoter sequences of these translation elongation factor genes harbour binding sites for transcription factors which are commonly deregulated in the pathogenesis of human cancers, such as cFos, cJun, c-Ets1, Sp1, Sp3, Pax2 and, Pax6 among others." (PMID 29342219, 2018). "Some of the differences between studies may be due to the methods used to modulate Sp expression since overexpression of Sp1 and Sp3 in some cancer cell lines induces apoptosis and inhibits growth." (PMID 26967243, 2016). "Our results clearly demonstrate for the first time that not only Sp1 but also Sp3 and Sp4 play a role in cancer cell growth, survival and migration/invasion of multiple cancer cell lines and regulate expression of gene products consistent with these observations." (PMID 26967243, 2016). "Studies in this laboratory have demonstrated that basal expression of genes, such as survivin, VEGF and EGFR, in various cancer cell lines is dependent on specificity protein (Sp) transcription factors Sp1, Sp3 and Sp4 which are highly expressed in many cancer cells and tumors." (PMID 26673922, 2015). "The functional importance of Sp1, Sp3 and Sp4 in cancer cells has been confirmed by RNA interference (RNAi) showing that knockdown of Sp transcription factors Sp1, Sp3 and Sp4 (singly or combined) decreases cell proliferation, survival, angiogenesis and inflammation." (PMID 26673922, 2015). "Alternatively, assessment of Sp1/Sp3 ratios in cancer cells may provide an additional prognostic marker for treatment with drugs like doxorubicin that cause cell cycle arrest." (PMID 17511886, 2007).
cancer (continued). "Estrogen receptor: The hormonal regulation of ER-responsive genes has been investigated in breast and other cancer cell lines, and induction or repression of many of these genes by ER ligands primarily involve ER interactions with DNA-bound Sp1 and, in a few cases, Sp3 or Sp4." (PMID 39858066, 2025). "Moreover, several anticancer agents including NSAIDs and GT-094 (a NO-NSAID), curcumin, betulinic acid and synthetic triterpenoids, and arsenic trioxide decrease expression of Sp1, Sp3, Sp4 and Sp-regulated genes in cancer cells and these effects contribute to their anticancer activity." (PMID 23110215, 2012). "However, the combined siRNA-mediated knockdown of Klf4 and Sp3 resulted in consistent up-regulation of Notch1 expression in both HKCs and cancer cells (HeLa and SCC13 cells), with the concomitant knock-down of Sp1 having no additional effects (C and data not shown)." (PMID 20442780, 2010). "In cancer cells, RARα/RXRα (NR1B1/NR2B1) interacts with Sp1 and Sp3 on the 17β-hydroxysteroid dehydrogenase type 2 (HSD17B2) promoter, and retinoic acid (RA) induces its expression." (PMID 39858066, 2025). "HNF4/Sp1 interactions that induce eosinophil RNase2 in cancer cells are also complex, where HNF-4/Sp1 and HNF-4/Sp3 activate the expression of human haem oxygenase-1 in hepatoma cells." (PMID 39858066, 2025). "Our results showed that miR-27a suppressed ZBTB10 in cancer cells and antisense miR-27a induced ZBTB10 expression with downregulation of Sp1, Sp3, Sp4 and pro-oncogenic Sp-regulated genes." (PMID 34072678, 2021). "A growing evidence indicate that downregulation of Sp1 and Sp3 expressions by drugs or RNA interference can induce autophagy by depressing EGFR activity and downstream the AKT/MAPK pathways in cancer cells 20,36." (PMID 32226300, 2020). "In summary, this study indicates that Sp1, Sp3 and Sp4 are NOA genes that are highly expressed in tumor vs. non-tumor tissue and regulate expression of pro-oncogenic factors that contribute to cancer cell growth, survival and migration/invasion." (PMID 26967243, 2016). "Further, it has been reported that knockdown or downregulation of Sp1, Sp3, and Sp4 represses expression of Sp-regulated genes, including VEGF and BCL-2, inhibits cancer cell growth, and induces apoptosis." (PMID 23626851, 2013). "Topological analysis of the combined networks revealed that many predicted interactions are disrupted in cancer, with E2F1, SP3 and NFκB1 emerging as major regulators." (PMID 22548828, 2012). "CENP-H can promote cancer growth and metastasis through PI3K/AKT, Survivin, and mitochondrial apoptosis signaling mechanisms, and it can be regulated by lncRNA PVT1/miR-612, Sp1, or Sp3." (PMID 40071086, 2025). "In summary, CENP-H is involved in cancer growth and metastasis through PI3K/AKT, survivin, and mitochondrial apoptosis signaling mechanisms and can be regulated by lncRNA PVT1/miR-612, Sp1, or Sp3." (PMID 40071086, 2025). "Other studies in cancer cell lines showed that several NR4A1-regulated integrins, including β1-, β4-, α5- and α6-integrins, were coregulated by NR4A1 interactions with Sp1, Sp3 and Sp4; however, the role of individual Sp TFs was gene and cell context-dependent." (PMID 39858066, 2025). "Stemness in breast cancer is maintained by the long non-coding RNA408 (Lnc408)—dependent recruitment of Sp3 to CBY1 gene promoters to inhibit expression of CBY1, which indirectly enhances levels of nuclear β-catenin and β-catenin regulated cancer stem cell-related genes." (PMID 36982239, 2023). "Moreover, betulinic acid exerted repressive effects on the levels of Sp1, Sp3 and Sp4 in tumor tissues of mice xenografted with BT474 cancer cells." (PMID 36615262, 2022). "Interestingly, quantities of Sp1, Sp3 and Sp4 were found to be suppressed in ZBTB4-overexpressing cancer cells." (PMID 36615262, 2022). "Sp1 and Sp3 regulate EGFR activity through interacting with HDAC1 and HDAC2 in cancer cells." (PMID 31196210, 2019).
cancer (continued). "After the analysis of TCGA HCC database, we observed that Bak transcription in cancer tissue was higher than that in non-cancer tissues, and its transcription was correlated with Sp1 and Sp3 transcription level." (PMID 29653560, 2018). "Globally, the dynamics of the SP3-CTP protein sets reveals large groups of proteins that display histotype-specific expression patterns and that have been characterized in the context of ovarian and other cancers." (PMID 27713570, 2016). "In this line, several members of the SP family of TFs, such as SP1, SP3 and SP4, have been found to play an important role in the pathogenesis of some cancers including sarcomas and may constitute relevant therapeutic targets." (PMID 27105533, 2016). "Although there are a few reports indicating that Sp1, Sp3 and Sp4 differentially regulate some genes and coregulate others, the functional roles of Sp3 and Sp4 compared to Sp1 in cancer cells have not been extensively investigated." (PMID 26967243, 2016). "It has also been reported that zinc depletion induces apoptosis and decreases Sp1, Sp3 and Sp4 in cancer cell lines, and we confirmed that aspirin-induced PARP cleavage and downregulation of Sp1, Sp3 and Sp4 was inhibited in RKO and SW480 cells cotreated with aspirin plus ZnSO4." (PMID 23110215, 2012). "Because the effects of Timeless depletion and SP3 overexpression have not been tested in normal cells, it remains unclear whether their effects are neither cancer-specific nor PEM-resistance-specific, which is a big limitation in this study." (PMID 38354174, 2024). "As Sp1 and Sp3 are overexpressed in most cancer types, have been characterized as non-oncogene addiction genes, and have been studied as potential biomarkers for recurrent PCa, these key findings highlight the importance of examining the AR, Sp1 and Sp3 signaling axis in PCa." (PMID 35018219, 2022). "Functional studies have demonstrated that the SP-like family of TFs regulates various genes responsible for cancer-related cellular mechanisms; SP1, SP3, and SP4 are also non-oncogene addiction (NOA) genes and thus are important drug targets." (PMID 37998757, 2023).